VASH2 (vasohibin 2)
Description:
Tyrosine carboxypeptidase that removes the C-terminal tyrosine residue of alpha-tubulin, thereby regulating microtubule dynamics and function. Critical for spindle function and accurate chromosome segregation during mitosis since microtubule detyrosination regulates mitotic spindle length and postioning. Acts as an activator of angiogenesis: expressed in infiltrating mononuclear cells in the sprouting front to promote angiogenesis. Plays a role in axon formation.
Synonyms: FLJ12505
Tractability: Small molecule: a structure with a bound ligand is known. Antibody: UniProt places it where antibodies can reach, with high confidence; its Gene Ontology location is reachable by antibodies, with medium confidence.
Gene: Protein-coding gene on chromosome 1 (212,950,520 to 212,992,838, forward strand). Ensembl gene ENSG00000143494.
Subcellular location: Cytoplasm; Secreted; Cytoplasm, cytoskeleton
Subcellular location (Human Protein Atlas): Cytosol; Predicted to be secreted
Pathways (Reactome):
Metabolism of proteins: Carboxyterminal post-translational modifications of tubulin
Gene Ontology:
Molecular function: actin binding; metallocarboxypeptidase activity; microtubule binding; protein binding; tubulin-tyrosine carboxypeptidase
Biological process: axon development; cell-cell fusion; positive regulation of angiogenesis; positive regulation of endothelial cell proliferation; proteolysis; regulation of angiogenesis
Cellular component: cytoplasm; cytosol; extracellular region; cytoskeleton
Genetic constraint (gnomAD): Loss-of-function variants: 28 observed, 37.89 expected, observed/expected ratio (o/e) 0.74, 90% interval 0.55 to 1.01. The upper end of that interval is the gene's LOEUF score, 1.01, which puts it in group 4 of 6, group 1 being the genes least tolerant of losing a copy. Missense variants: 419 observed, 451.89 expected, observed/expected ratio (o/e) 0.93, 90% interval 0.86 to 1. Synonymous variants: 188 observed, 171.89 expected, observed/expected ratio (o/e) 1.09, 90% interval 0.97 to 1.23.
Homologues: Orthologues: chimpanzee VASH2 (100% identical), macaque VASH2 (99% identical), dog VASH2 (99% identical), guinea pig VASH2 (97% identical), mouse Vash2 (97% identical), rat Vash2 (97% identical), rabbit VASH2 (94% identical), pig VASH2 (81% identical), tropical clawed frog vash2 (75% identical), zebrafish vash2 (65% identical). Paralogues in human: VASH1 (53% identical).
Diseases named in the same sentence as VASH2 in open-access papers:
VASH2 is named in the same sentence as 44 diseases in open-access papers, as found by Europe PMC text mining. Sharing a sentence is not in itself a finding about the gene and the disease. The quoted sentences say what the papers report.
breast carcinoma (10 papers, 2014 to 2023). "VASH2 expression in cancer could be associated with the progression and poor clinical prognosis including pancreatic and breast carcinomas." (PMID 29641565, 2018). "It was hypothesized that VASH2 is associated with cell proliferation in breast cancer, and in order to investigate the proliferative function of VASH2 in breast cancer cells and the underlying mechanism, VASH2 overexpression and knockdown in vitro and in vivo models were established." (PMID 24920244, 2014). "Among other functions, VASH2 has been reported to be involved in mammary tumour development in dogs and to enhance angiogenesis in mice." (PMID 34474664, 2021). "Higher expression of VASH2 induces expression of growth factors and promotes cell proliferation in breast cancer." (PMID 30517191, 2018). "Analysis of the models indicated that VASH2 promotes the proliferation of breast cancer cells in vitro and in vivo." (PMID 24920244, 2014). "VASH2 expression was investigated in human breast cancer in the current study; rabbit polyclonal anti-human VASH2 antibodies were produced and successfully used in immunoblotting and immunohistochemical analysis." (PMID 24920244, 2014). "In the present study, VASH2 expression in clinical human breast cancer tissues was investigated, and significantly higher levels of VASH2 in grade 3 and Ki67 ≥14% breast cancer tissues were detected." (PMID 24920244, 2014). "VASH2 expression levels in 99 human breast cancer tissue samples were assessed by immunohistochemical analysis." (PMID 24920244, 2014). "The results indicated that the expression level of cytoplasmic VASH2 was higher in breast cancer tissues with a Ki67 (a proliferation marker) level of ≥14%, compared with tissues with a Ki67 level of <14%." (PMID 24920244, 2014). "MCF-7 and BT474 human breast cancer cells were transfected with lentiviral constructs to generate in vitro VASH2 overexpression and knockdown models." (PMID 24920244, 2014). "The present study demonstrated a high level of VASH2 expression in breast cancer cells, and that VASH2 functions as an inducer of growth factor expression, promoting cell proliferation in breast cancer." (PMID 24920244, 2014). "Human growth factor array demonstrated that VASH2 promoted proliferation in breast cancer cells via the upregulation of FGF2 and growth/differentiation factor-15 (GDF15) expression." (PMID 24920244, 2014). "Recently, VASH2 has been demonstrated to be involved in the malignant behavior of a number of malignancies, including hepatic cancer, ovarian cancer, endometrial cancer, gastrointestinal cancers, breast cancer, and pancreatic cancer." (PMID 28327155, 2017). "The current study identified a novel role for VASH2 in human breast cancer, and this knowledge suggests that VASH2 may be a novel target in breast cancer treatment." (PMID 24920244, 2014). "The present study identified a novel role for VASH2 in human breast cancer, and this knowledge may lead to the possibility of VASH2 as a novel target in breast cancer treatment." (PMID 24920244, 2014). "We previously produced rabbit polyclonal anti-human VASH2 antibodies which were successfully applied in immunoblotting and immunohistochemical analyses of human liver cancer and adjacent normal tissues, breast cancer, and multiple other human cancer and normal tissues." (PMID 28327155, 2017). "In the current study VASH2 expression in human breast cancer tissue and adjacent non-cancerous tissue was investigated with immunohistochemistry." (PMID 24920244, 2014).
glioma (9 papers, 2018 to 2023). A benign or malignant brain and spinal cord tumor that arises from glial cells (astrocytes, oligodendrocytes, ependymal cells). "In glioma microvessels, the overexpression of H19 induces glioma-associated endothelial cells (GECs) proliferation, migration and tube formation via increasing the expression of angiogenic factor VASH2 as a miR-29a sponge." (PMID 29458374, 2018). "Knockdown of H19 has been revealed to inhibit glioma-induced angiogenesis and glioma-associated endothelial cell capabilities of proliferation, migration and tube formation by decreasing the expression of angiogenic factor vasohibin 2 through upregulation of miR-29a." (PMID 31757932, 2019). "In glioma, H19 increases vasohibin 2 (VASH2) levels and Wnt/β-catenin signaling via impairing the action of miR-29a-3p and miR-342, respectively, actuating angiogenesis as a consequence." (PMID 34298879, 2021). "For instance, VASH2 has been shown promote angiogenesis in tumors and H19 lncRNA—highly expressed in glioma cells—upregulates VASH2 through the H19/miR-29a/ VASH2 axis." (PMID 31404273, 2019). "One latest study exhibits that lncRNA-H19 inhibits miR-29a to upregulate the angiogenic factor VASH2 and modulate proliferation and tube formation of glioma vascular ECs in vitro." (PMID 29673400, 2018). "Accordingly, the knockdown of lncRNA H19 resulted in miR-29a upregulation and the downregulation of its target, vasohibin 2 (VASH2), in ECs, ultimately leading to the inhibition of glioma-induced EC angiogenesis in vitro." (PMID 37443725, 2023).
hepatocellular carcinoma (9 papers, 2013 to 2024). A malignant tumor that arises from hepatocytes. "Previously, we reported that Vasohibin2 (VASH2) is preferentially expressed in hepatocellular carcinoma (HCC) tumor tissues and promotes angiogenesis." (PMID 25269476, 2014). "VASH2 is also highly expressed in hepatocellular carcinoma cells (HCCs) and tissues, and promotes HCC angiogenesis and malignant transformation." (PMID 24885408, 2014). "VASH2 is reportedly expressed in many common tumors, like hepatocellular carcinoma, serous ovarian adenocarcinoma and gastric cancer, and participates in the program of tumor metabolism, such as angiogenesis." (PMID 24595063, 2014). "In addition, VASH2 is expressed in ovarian or hepatocellular carcinoma cells." (PMID 25184477, 2014). "In one study, an autocrine and paracrine mode of action for VASH2 was found to enhance the expression of FGF-2 and VEGF by nuclear factor-κB upregulation in hepatocellular carcinoma (HCC) cells." (PMID 23426782, 2013). "The methylation of specific genes, including VASH2, CHFR, GRID2IP, CCNJ, SEPT9, and F12, is considered a biomarker for the onset of hepatocellular carcinoma (HCC)." (PMID 38473997, 2024).
ovarian carcinoma (8 papers, 2014 to 2024). A malignant neoplasm originating from the surface ovarian epithelium. "In addition, VASH2 expression was associated with accelerated angiogenesis in human ovarian cancer, and downregulation of VASH2 in endometrial cancer cells inhibited tumor angiogenesis." (PMID 32604722, 2020). "The administration of siRNA targeting VASH2 or neutralizing anti‐VASH2 monoclonal antibody has been shown to suppress tumor angiogenesis and progression in a murine xenograft model of ovarian cancer." (PMID 39710372, 2024). "VASH2 is produced by various cancer cells, including ovarian cancer, and promotes tumor growth by accelerating angiogenesis." (PMID 33710778, 2021). "Tumor angiogenesis was abrogated by the specific knockdown of intrinsic VASH2 in ovarian cancer cells, which inhibited tumor growth, peritoneal dissemination, and ascites production." (PMID 33710778, 2021). "The effects of the VASH2 knockout on cell growth were evaluated based on comparisons of the growth of control and VASH2 knockout ovarian cancer cell lines in vitro." (PMID 33710778, 2021). "We herein established several VASH2 knockout ovarian cancer cell lines using the CRISPR/Cas9 genome editing system to examine the intracellular tubulin detyrosination status and PTX chemosensitivity." (PMID 33710778, 2021). "VASH2 expression has been demonstrated in certain ovarian cancers, where it promotes tumor growth and peritoneal dissemination of tumor cells by stimulating tumor angiogenesis." (PMID 24885408, 2014). "Paclitaxel (PTX), an effective chemotherapeutic agent that is widely used to treat ovarian cancer, inhibits microtubule depolymerization and may interact with VASH2." (PMID 33710778, 2021). "The VASH2 knockout ovarian cancer cell lines SKOV‐3/sgVASH2 and SHIN‐3/sgVASH2 were established." (PMID 33710778, 2021). "Therefore, we herein established several VASH2 knockout ovarian cancer cell lines using the CRISPR/Cas9 genome editing system to examine the intracellular tubulin detyrosination status and PTX chemosensitivity." (PMID 33710778, 2021). "The inhibition of angiogenesis and regulation of microtubule activity may be expected with ovarian cancer treatment strategies targeting VASH2." (PMID 33710778, 2021). "The inhibition of angiogenesis and regulation of microtubule activity may be expected in ovarian cancer treatment strategies targeting VASH2." (PMID 33710778, 2021). "The inhibition of angiogenesis and regulation of microtubule activity may be achieved in ovarian cancer treatment strategies targeting VASH2." (PMID 33710778, 2021). "Furthermore, the exogenous administration of siRNA targeting VASH2 with atelocollagen biomaterial to a murine xenograft model of ovarian cancer retarded tumor growth by suppressing angiogenesis." (PMID 33710778, 2021). "VASH2 is also involved in the proliferation of hepatic and ovarian cancers." (PMID 30517191, 2018). "Thus, targeting VASH2 may also represent a promising therapeutic strategy for ovarian cancer." (PMID 39710372, 2024). "In conclusion, the knockout of VASH2 reduced TCP activity, increased cyclin B1 expression, and increased PTX chemosensitivity in ovarian cancer cells." (PMID 33710778, 2021). "The knockout of VASH2 reduced TCP activity and increased cyclin B1 expression, resulting in increased PTX chemosensitivity in ovarian cancer cells." (PMID 33710778, 2021). "In the present study, we demonstrated that the knockout of the angiogenesis stimulator, vasohibin‐2 (VASH2) reduced tubulin carboxypeptidase (TCP) activity, increased cyclin B1 expression, and increased paclitaxel chemosensitivity in ovarian cancer cells." (PMID 33710778, 2021). "Thus, the specific knockout of VASH2 may be induced in ovarian cancer cells using CRISPR/Cas9." (PMID 33710778, 2021). "In ovarian cancer cells, the ablation of VASH2 reduced CCP activity and increased cyclin B1 expression results in increased paclitaxel sensitivity in ovarian cancer cells." (PMID 35008169, 2021).
ovarian carcinoma (continued). "Vasohibin-2 (VASH2) is an endothelium-derived angiogenic factor expressed in cancer cells that promotes tumor growth and peritoneal dissemination in ovarian cancer." (PMID 32780245, 2020). "In the present study, VASH2 knockout cells weakly expressed detyrosinated tubulin, suggesting that VASH2 exhibits TCP activity and may play an important role in the accumulation of detyrosinated tubulin in ovarian cancer cells." (PMID 33710778, 2021). "The knockout of VASH2 did not affect the proliferation or sphere‐forming activity of ovarian cancer cells in vitro." (PMID 33710778, 2021). "On the contrary, the knockout of VASH2 did not affect sensitivity to CDDP in ovarian cancer cell lines, and this may be because CDDP is a drug that targets DNA itself, not microtubules." (PMID 33710778, 2021). "However, the knockout of VASH2 did not completely inhibit tubulin detyrosination and had a negligible effect on the in vitro proliferation and sphere‐forming activity of ovarian cancer cells in 2D or 3D cell cultures, suggesting that microtubule functions are preserved." (PMID 33710778, 2021). "Collectively, these results demonstrated that the knockout of VASH2 increased sensitivity to PTX, but not to CDDP in ovarian cancer cells." (PMID 33710778, 2021). "The knockout of VASH2 significantly increased chemosensitivity to PTX, but not to cisplatin in ovarian cancer cell lines." (PMID 33710778, 2021). "Furthermore, the knockout of VASH2 significantly increased sensitivity to PTX, but not to CDDP in ovarian cancer cell lines." (PMID 33710778, 2021).
pancreatic cancer (6 papers, 2017 to 2023). "Here we investigated the association of VASH2 expression and chemoresistance in pancreatic cancer." (PMID 28327155, 2017). "Hh signaling is also associated with cellular communication network factor 1 (CCN1), Notch1, Vasohibin 2 (VASH2), and Ski in pancreatic cancer." (PMID 34440799, 2021). "Human pancreatic cancer tissues from 102 patients were subjected to immunohistochemical staining for VASH2 and RRM2." (PMID 28327155, 2017). "We demonstrate that VASH2 is overexpressed in human pancreatic cancer and functions as a gemcitabine-resistance factor by Jun proto-oncogene (JUN) dependent transactivation of ribonucleotide reductase regulatory subunit M2 (RRM2)." (PMID 28327155, 2017). "Here we report that the gemcitabine metabolism related gene, RRM2, is upregulated in pancreatic cancer models of VASH2 overexpression." (PMID 28327155, 2017). "We investigated the levels of VASH2 expressed in 102 human pancreatic cancer tissue samples and paired adjacent tissues by immunohistochemical analysis." (PMID 28327155, 2017). "To further investigate the involvement of VASH2 in gemcitabine resistance, we created pancreatic cancer models of VASH2 overexpression and knockdown, and observed that VASH2 inhibited gemcitabine-induced apoptosis in vitro and in vivo." (PMID 28327155, 2017). "VASH2 protein expression was higher in human pancreatic cancer than in paired adjacent tissues and elevated VASH2 levels were associated with gemcitabine chemoresistance." (PMID 28327155, 2017). "Collectively, these results indicate that VASH2 induces gemcitabine resistance via upregulation of RRM2 in human pancreatic cancer." (PMID 28327155, 2017). "To further investigate the impact of VASH2 on pancreatic cancer sensitivity to gemcitabine in vivo we analyzed the tumor control rate using a xenograft model of subcutaneous tumor growth in nude mice." (PMID 28327155, 2017). "Immunohistochemical analysis demonstrated that the expression of VASH2 was positively related to the RRM2 in human pancreatic cancer tissues." (PMID 28327155, 2017). "We also investigated the function and mechanism of VASH2 in human pancreatic cancer using in vitro and in vivo models." (PMID 28327155, 2017). "In this study, we investigated the expression of VASH2 in human pancreatic cancer, and found significantly higher levels of VASH2 in pancreatic cancer tissues than in paired cancer-adjacent normal tissue." (PMID 28327155, 2017). "The proportion of specimens exhibiting middle/strong staining for VASH2 was significantly higher in pancreatic cancer tissue samples (56.9%, 58/102) than in adjacent normal tissue samples (24.5%, 25/102; P = 0.001)." (PMID 28327155, 2017). "In cell line models of pancreatic cancer, VASH2 expression induced gemcitabine chemoresistance in vitro and in vivo." (PMID 28327155, 2017). "It was discovered that expression of ribonucleotide reductase regulatory subunit M2 (RRM2) is regulated by VASH2; immunohistochemical analysis demonstrated a positive association of VASH2 expression and RRM2 expression in human pancreatic cancer tissues." (PMID 28327155, 2017). "Here, we investigated the expression of VASH2 in human pancreatic cancer and analyzed the relationship between VASH2 expression and clinical features." (PMID 28327155, 2017). "The proportion of specimens with middle/strong staining for VASH2 expression was generally higher in grade 3 pancreatic cancers than in grade 1-2 pancreatic cancers (37/54 [68.5%] vs. 21/48 [43.8%], respectively; P = 0.012)." (PMID 28327155, 2017). "VASH2 overexpression results in strongly increased migration of human pancreatic cancer cells." (PMID 33614664, 2021). "Based on previous findings, we hypothesized that Vasohibin 2 (VASH2) protein may induce epithelial‐mesenchymal transition (EMT) of pancreatic cancer (PC) cells by promoting the malignant behaviors of these cells." (PMID 30318866, 2018).